XRCC1 (X-ray repair cross complementing 1)
Diseases named in the same sentence as XRCC1 in open-access papers (continued):
Sharing a sentence is not in itself a finding about the gene and the disease.
gastric cancer (continued). "Surprisingly, although JWA and XRCC1 function as DNA repair proteins had synergistic effect in normal gastric epithelial cells, opposite effects were shown in cisplatin resistant gastric cancer cells." (PMID 25476899, 2014). "Furthermore, in the context of gastric cancer, it has been reported that XRCC1 expression was significantly elevated in cisplatin-resistant cells, and it independently promoted cisplatin resistance." (PMID 37679817, 2023). "In the current study, we studied whether the polymorphisms in the two DNA repair genes, XRCC1 and XPD, involved in BER and NER pathways, respectively, are implicated in the development of gastric cancer in the Kashmiri population." (PMID 30225185, 2018). "Furthermore, TXNL1 can resist cisplatin by interacting with X-ray repair cross complementing group 1 (XRCC1) in human gastric cancer." (PMID 30290847, 2018). "Interestingly, as JWA upregulated XRCC1 expression in normal cells, JWA downregulated XRCC1 expression through promoting the degradation of XRCC1 in cisplatin-resistant gastric cancer cells." (PMID 25476899, 2014). "Notably, they discovered that ARL6IP5 had contrasting effects on XRCC1 in gastric carcinoma cells compared to their normal counterparts; on gastric carcinoma cells ARL6IP5-OE decreased XRCC1 levels, while in their normal counterparts ARL6IP5-OE increased XRCC1 levels." (PMID 35293383, 2022). "Besides, high expression of XRCC1 has also been found in glioma and gastric cancer." (PMID 32258128, 2020). "Previous studies have found that polymorphisms of the DNA repair gene X-ray repair cross-complementing group 1(XRCC1) and environmental factors are both associated with an increased risk of stomach cancer, but no study has reported on the potential additive effect of these factors among Thai people." (PMID 29020930, 2017). "JWA alone and in combination with XRCC1, FAK, MMP2, MMD2 can predict the prognosis of gastric cancer patients." (PMID 36230577, 2022). "In summary, in cisplatin-resistant gastric cancer cells, JWA is involved in reversing the chemoresistance process by blocking the XRCC1-dependent DNA repair pathway and promoting the DR4 receptor-dependent apoptosis pathway." (PMID 36230577, 2022). "We demonstrate that high fat and salt intake are particularly risky for the XRCC1 Arg/Arg genotype, and importantly, these environmental factors could not be shown to be associated with increased risk of stomach cancer in the Gln/Arg or Gln/Gln XRCC1 genotypes." (PMID 29020930, 2017). "In addition, JP3 competitively inhibits the binding of XRCC1 and CK2 in cisplatin-resistant gastric cancer cells, and JP3 in combination with cisplatin synergistically promotes DNA damage and apoptosis gastric cancer." (PMID 36230577, 2022). "However, no study has established differential stomach cancer risks of salt and fat intake for different XRCC1 genotypes." (PMID 29020930, 2017).
colorectal cancer (32 papers, 2003 to 2025). A primary or metastatic malignant neoplasm that affects the colon or rectum. "In colorectal cancer, for example, polymorphisms in genes such as XRCC1 and ERCC1 have been linked to variations in recurrence‐free and overall survival, underscoring their prognostic relevance." (PMID 40833230, 2025). "In this follow-up research, we observed the interaction of these gene polymorphisms (COMT, GSTM1, GSTT1, MGMT, NQO1, and XRCC1) with different meat diets and on outcomes linked to colorectal cancer risk: ATNC levels, DNA adduct levels, and DNA strand breaks." (PMID 38337709, 2024). "Our results indicate that the frequency of the Gln (A) allele of XRCC1 (rs25487) is significantly higher in colorectal cancer patients, compare to controls (p = 0.01, OR: 1.54, 95% CI 1.9–13.3)." (PMID 32711416, 2020). "The outcomes of some investigation about the association of XRCC1 (rs25487) polymorphism with colorectal cancer risk have been contradictory." (PMID 32711416, 2020). "The biological interaction between XRCC1 polymorphism and smoking in colorectal cancer risk is probable." (PMID 32711416, 2020). "OGG1 directly interacts with XRCC1, and the OGG1 rs1052134 showed epistasis with two XRCC1 SNPs in colorectal cancer risk." (PMID 27588484, 2016). "The objective of this study is to investigate the association among the polymorphisms of XRCC1 gene, smoking, drinking, family history of tumors, and the risk of colorectal cancer (CRC) in the population of Han nationality in Jiangsu Province, China." (PMID 26271249, 2015). "The aim of this study was to investigate the role of the XRCC1 Arg399Gln polymorphism in the susceptibility of a Kashmiri population to colorectal cancer (CRC)." (PMID 23426866, 2013). "A study in Egypt reported that individuals with the XRCC1 399Gln allele had an approximately 4-fold risk of colorectal cancer as compared with those with the XRCC1 399Arg/Arg genotype, although the number of subjects was small." (PMID 22186158, 2012). "The results showed that the XRCC1 399Gln/Gln genotype was associated with an increased risk of colorectal cancer and that the increase was greatest in those with high alcohol consumption." (PMID 22186158, 2012). "The XRCC1 399Gln/Gln genotype was significantly associated with colorectal cancer risk (adjusted odds ratio [OR] 1.57, 95% CI 1.01–2.42; relative to 399Arg/Arg genotype)." (PMID 22186158, 2012). "First, this is the largest published study to examine the association between XRCC1 polymorphisms and colorectal cancer in Japan." (PMID 22186158, 2012). "An interaction effect between XRCC1 polymorphisms and alcohol consumption on colorectal cancer risk is biologically plausible." (PMID 22186158, 2012). "In this study, we investigated the associations between genetic polymorphisms in the DNA repair gene XRCC1 and colorectal cancer risk." (PMID 22186158, 2012). "In the present study, we examined the associations of these 3 genetic polymorphisms of the XRCC1 gene with colorectal cancer and the impact of the association between alcohol consumption and colorectal cancer risk in Japan." (PMID 22186158, 2012). "OGG1 Ser326Cys, APEX1 Asp148Glu and XRCC1 Arg399Gln have also been linked to a risk of colorectal cancer." (PMID 18823566, 2008). "Previous reports have revealed significant associations between XPD or XRCC1 gene polymorphisms and survival of lung or colorectal cancer patients treated with platinum-based chemotherapy or radiotherapy." (PMID 16880786, 2006). "Combinations of XRCC1 Arg280His and XRCC1 Arg399Gln polymorphisms and risk of colorectal carcinomas and adenomas." (PMID 16542436, 2006). "Our results do not appear to be entirely consistent with the results of some previous reports, the former group reporting that the XRCC1 399Gln allele significantly increased the risk of colorectal cancer (OR = 3.98, 95% CI = 1.50–10.6)." (PMID 15679883, 2005).
colorectal cancer (continued). "The findings are additional evidence that individuals with the XRCC1 399Gln/Gln genotype have an increased risk of colorectal cancer, and that XRCC1 polymorphisms have an important role in colorectal cancer risk associated with alcohol consumption or gene-gene interaction." (PMID 22186158, 2012). "Therefore, we examined the associations of XRCC1 Arg399Gln, Arg280His, and Arg194Trp polymorphisms with colorectal cancer and the impact of the association between alcohol consumption and colorectal cancer risk." (PMID 22186158, 2012). "Although we didn't find any significant independent associations between these DNA-repair genes and colorectal cancer risk, the risk appeared to be slightly increased for individuals who featured the XRCC1 399Arg/Arg, XRCC3 241Thr/Thr genotypes and the XPD 751Gln allele." (PMID 15679883, 2005). "In conclusion, the findings add evidence to the hypothesis that individuals with the XRCC1 399Gln/Gln genotype are at increased risk of colorectal cancer and that XRCC1 polymorphisms have an important role in colorectal cancer risk related to alcohol consumption or gene-gene interaction." (PMID 22186158, 2012). "In the current study, we examined the association of SNPs in the genes XRCC1-rs25487, ERCC1-rs11615, ERCC2-rs238406, and ERCC2-rs13181 with colorectal cancer (CRC) risk, relapse-free survival (RFS), overall survival (OS), and toxicity during chemotherapy." (PMID 32397974, 2020). "This study was designed to investigate the association between XRCC1 (rs25487) and OGG1 (rs1052133) polymorphisms and susceptibility to colorectal cancer (CRC) in the Ahvaz city, south-west Iran." (PMID 32711416, 2020). "Incidentally, the XRCC1 rs1799782 synergistically interacted (crude ORinteraction = 1.13) with the MUTYH rs3219489, albeit weakly, in colorectal cancer risk." (PMID 27588484, 2016). "It has been observed that patients with colorectal cancer have high XRCC1 expression levels that are related to microsatellite instability." (PMID 25268610, 2014). "In view of the role of the polymorphism in BER enzymes in colorectal carcinogenesis, we evaluated the influence of the APE1 Asp148Glu polymorphism on APE1, XRCC1, PARP1 and OGG1 expression in normal and tumor samples from patients with colorectal cancer." (PMID 25268610, 2014). "In summary, our data show that patients with colorectal cancer present expression changes in several BER genes, suggesting a role for APE1, XRCC1, PARP1 and OGG1 and APE1 polymorphism in colorectal carcinogenesis." (PMID 25268610, 2014). "Tumor site- and tumor-node-metastasis stage-specific hazard ratios for the associations between the coexisting XRCC1 Arg399Gln and XPD Lys751Gln allelic variants and overall survival among colorectal cancer patients." (PMID 23894404, 2013). "Tumor site- and tumor-node-metastasis stage-specific hazard ratios for the associations between the XRCC1 Arg399Gln and XPD Lys751Gln allelic variants and overall survival among colorectal cancer patients." (PMID 23894404, 2013). "Therefore, the risk of colorectal cancer might be attributable to the combined genotypes of XRCC1." (PMID 22186158, 2012). "This protective role of the XRCC1 399Gln allele is in contrast to previous reports on this BER gene polymorphism and colorectal cancer risk." (PMID 16542436, 2006). "Combined effects of polymorphisms of the XRCC1 Arg399Gln, XRCC3 Thr241Met and XPD Lys751Gln genes in regard to colorectal cancer risk were observed in the present study." (PMID 15679883, 2005). "This study was designed to examine the polymorphisms associated with three DNA repair genes, namely: XRCC1 Arg399Gln, XRCC3 Thr241Met and XPD Lys751Gln, and investigate their role as susceptibility markers for colorectal cancer." (PMID 15679883, 2005).
colorectal cancer (continued). "Therefore, this study was designed to investigate the association between the polymorphisms of DNA repair genes, including XRCC1 (rs25487) and OGG1 (rs1052133) given their susceptibility to colorectal cancer in the Ahvaz city, south-west Iran." (PMID 32711416, 2020). "Thus, we evaluated the influence of APE1 T2197G (Asp148Glu) polymorphism on APE1, XRCC1, PARP1 and OGG1 expression in normal and tumor samples from patients with colorectal cancer." (PMID 25268610, 2014). "Interestingly, the polymorphisms in XRCC1 and MDR1 have been associated with clinical outcomes in gastric and colorectal cancer." (PMID 25232828, 2014). "Thus, taking into account the role of BER in colorectal carcinogenesis, the effects of the APE1 Asp148Glu polymorphism on APE1, XRCC1, PARP1 and OGG1 gene expression were evaluated in patients with colorectal cancer." (PMID 25268610, 2014). "In contrast, other case-control studies in various countries did not observe a positive association between the XRCC1 399Gln allele and the risk of colorectal cancer." (PMID 22186158, 2012). "We conducted a case-control study including 727 cases of cancer and 736 hospital-based age- and sex-matched healthy controls to examine the role of genetic polymorphisms of three DNA-repair genes (XRCC1, XRCC3 and XPD) in the context of colorectal cancer risk for the Taiwanese population." (PMID 15679883, 2005). "Our results suggest that genetic polymorphisms of the XRCC1, XRCC3 and XPD genes, particularly in combination, may be associated with an individual's susceptibility to colorectal cancer." (PMID 15679883, 2005). "However, a recent publication showed a lack of correlation between XRCC1 gene polymorphisms and colorectal cancer susceptibility in a Malaysian cohort." (PMID 29312615, 2017). "The risk for colorectal cancer was not significantly different for individuals featuring the XRCC1 399Arg/Arg genotype (OR = 1.18; 95% CI, 0.96–1.45), the XRCC3 241Thr/Thr genotype (OR = 1.25; 95% CI, 0.88–1.79) or the XPD 751Gln allele (OR = 1.20; 95% CI, 0.90–1.61)." (PMID 15679883, 2005). "Distributions of XRCC1 Arg194Trp, XRCC1 Arg280His, XRCC1 Arg399Gln, XRCC3 Thr241Met and XPD Lys751Gln genotypes and development of colorectal carcinomas and adenomas." (PMID 16542436, 2006). "We have compared the frequency of polymorphisms in the NER genes, XPD, XPF, XPG, ERCC1; in the BER gene, XRCC1; and in the RR gene, XRCC3; in colorectal cancer patients and in a control group." (PMID 12865926, 2003). "In this study, we have compared the frequency of polymorphisms in the NER genes (XPD, XPF, XPG, ERCC1), and in XRCC1 and XRCC3 in colorectal cancer patients and a control group." (PMID 12865926, 2003). "Furthermore, our data show that patients with colorectal cancer present expression changes in several BER genes, suggesting a role for APE1, XRCC1, PARP1 and OGG1 in colorectal carcinogenesis." (PMID 25268610, 2014).
ovarian carcinoma (31 papers, 2013 to 2025). A malignant neoplasm originating from the surface ovarian epithelium. "On the other hand, other studies suggest that the combination of the XRCC1 194Trp and 399Gln alleles is associated with a significantly reduced risk of ovarian cancer mortality, compared to the presence of these variants individually." (PMID 40647471, 2025). "Mre11 blockade is a platinum sensitizer and can induce synthetic lethality in XRCC1 deficient-platinum sensitive ovarian cancers." (PMID 35853939, 2022). "Pre-clinically, Mre11 depletion or blockade not only reversed platinum resistance, but we also identified a synthetic lethality approach targeting Mre11 in XRCC1 deficient platinum sensitive ovarian cancers." (PMID 35853939, 2022). "We have previously shown that low XRCC1 protein expression (seen in about 33% of epithelial ovarian cancers) is associated with platinum sensitivity." (PMID 35853939, 2022). "Overexpression of XRCC1 in ovarian cancer has previously been associated with platinum-based drug resistance." (PMID 36551731, 2022). "Pre-clinically, Mre11 depletion or blockade not only reversed platinum resistance, but targeting Mre11 in XRCC1 deficient platinum sensitive ovarian cancers also induced synthetic lethality." (PMID 35853939, 2022). "In the current study, we analyze the associations between 19 SNPs of six BER-related genes (hOGG1, APE1, PARP1, FEN1, LIG3 and XRCC1) and ovarian cancer risk by genotyping method in 196 patients and 272 controls." (PMID 33391423, 2021). "Overexpression of XRCC1 contributes to the development of ovarian cancer and its high expression was associated with advanced malignancy and poor clinical outcomes in ovarian cancer patients." (PMID 32258128, 2020). "XRCC1 expression has been suggested as a predictive biomarker in human ovarian cancer with expression being associated with platinum resistance, suggesting that XRCC1 positive tumours should be considered for non platinum based chemotherapy." (PMID 29925418, 2018). "In ovarian cancer patients XRCC1 polymorphisms are associated with poorer prognosis and higher levels of platinum resistance." (PMID 29925418, 2018). "In the multivariate analysis, XRCC1 expression was independently associated with survival in ovarian cancer patients [HR 2.3, p = 0.002]." (PMID 23451157, 2013). "Our data provides evidence that ATR inhibition is suitable for synthetic lethality application and cisplatin chemopotentiation in XRCC1 deficient ovarian cancer cells." (PMID 23451157, 2013). "Importantly, Mre11 inhibition was synthetically lethal in platinum sensitive XRCC1 deficient ovarian cancer cells and 3D-spheroids." (PMID 35853939, 2022). "Additionally, high mRNA levels of XRCC1 and XRCC7 were only linked to a poor PFS in ovarian carcinoma patients (XRCC1: HR=1.29 (1.12-1.48), P=0.0004; XRCC7: HR=1.3 (1.14-1.48), P=0.0000), and were not linked to OS in all ovarian malignance patients." (PMID 34539898, 2021). "Taken together, the data implies that LIG1 blockade by small molecule inhibitor could be a promising strategy in XRCC1 deficient or proficient ovarian cancers." (PMID 34373746, 2021). "L82 monotherapy was synthetically lethal in XRCC1 deficient ovarian cancer cells and 3D-spheroids." (PMID 34373746, 2021). "Taken together, the data suggest that LIG1 specific inhibitor monotherapy or in combination with PARP inhibitor could be a novel synthetic lethality strategy in XRCC1 deficient ovarian cancers." (PMID 34373746, 2021). "In response to platinum-based chemotherapy, ovarian cancer patients with the XRCC1 194Trp/Trp genotype had a longer survival time compared to patients with the Arg/Arg genotype." (PMID 40647471, 2025). "In a study involving 195 patients with epithelial ovarian cancer, it was observed that 45% of patients with XRCC1-positive tumours were resistant to platinum drugs." (PMID 37679817, 2023).